TMEM271 (transmembrane protein 271)
Gene: Protein-coding gene on chromosome 4 (573,880 to 576,295, reverse strand). Ensembl gene ENSG00000273238.
Subcellular location: Membrane
Gene Ontology:
Cellular component: membrane
Homologues: Orthologues: macaque TMEM271 (97% identical), pig TMEM271 (88% identical), chimpanzee TMEM271 (86% identical), rat Tmem271 (84% identical), mouse Tmem271rt (83% identical).